HDAC2 (histone deacetylase 2)
Diseases named in the same sentence as HDAC2 in open-access papers (continued):
Sharing a sentence is not in itself a finding about the gene and the disease.
breast cancer (continued). "In contrast, when FOXA1 is deacetylated by HDAC2, it may bind to chromatin regions that are less likely to be enriched with ER binding, driving transcription independently of ER in breast cancer." (PMID 41224124, 2025). "Moreover, significant differences in semiquantitative HDAC2 expression were identified between groups G1 and G3 (p=0.007) and G1 and G4 (p=0.035), indicating lower HDAC2 expression in mammary carcinomas relative to normal tissue." (PMID 40590021, 2025). "Future trials should, thus, focus on the role of HDAC-2 in triple negative breast cancer, by explicitly using or, at least, distinguishing triple negative breast cancer samples from other breast cancer subtypes that evidently exhibit distinctive molecular patterns." (PMID 38201636, 2024). "Thus, ARAP1-AS1 exacerbates the development of breast cancer by inducing the transcriptional suppression of PLIN1 through the deacetylation activity of HDAC2 on the PLIN1 promoter." (PMID 39090630, 2024). "Our results are in line with the previously reported worse survival rate of cancer patients with overexpressing class I HDACs, especially HDAC1 and HDAC3 in lung cancers, HDAC2 in liver or breast cancers, and HDAC1/2/3 in ovarian cancers, gastric cancers, or sarcomas." (PMID 39063083, 2024). "HDAC-2 has been stated to play an important role in various breast cancer subtypes." (PMID 38201636, 2024). "A previous study indicates that HDAC2 could arise as a new potential index of aggressiveness and a therapeutic target against breast cancer." (PMID 38254989, 2024). "Interestingly, numerous study groups recently also explored the role of HDAC-2 in breast cancer and highlighted its oncogenic capacities in different breast cancer types." (PMID 38201636, 2024). "The results demonstrated that the colony formation ability of MDA-MB-231 cells was reduced after the knockdown of HDAC2, indicating that HDAC2 may serve as a potential therapeutic target for breast cancer." (PMID 37483962, 2023). "HDAC2 inhibition is a potential anti-cancer agent against breast cancer." (PMID 37764768, 2023). "In addition, histone deacetylase 2 (HDAC2)-dependent deacetylation of membrane PD-L1 promotes its nuclear translocation, regulating the immune response in breast cancer and colon cancer." (PMID 36977660, 2023). "High levels of HDAC2 were reported in aggressive basal-like breast cancer and could predict a poor prognosis in breast cancer patients." (PMID 36968022, 2023). "However, their HDAC2 inhibitory effects should be further confirmed and evaluated in breast cancer cells." (PMID 37764768, 2023). "A study reported that valeric acid significantly decreases HDAC2 activity in treated breast cancer cells and may lead to alterations of DNA methylation." (PMID 37764768, 2023). "Taken together, these findings suggested that HDAC2-targeting intervention could represent an effective approach for breast cancer control." (PMID 37764768, 2023). "The combination of GE and SFN downregulated HDAC2 protein levels in breast cancer cells." (PMID 37764768, 2023). "High levels of HDAC2 could predict the poor prognosis of breast cancer patients who received chemotherapy containing anthracyclines." (PMID 36968022, 2023). "We aimed to assess the clinical importance of HDAC-2 in breast cancer (BC)." (PMID 36294811, 2022). "Furthermore, YAP/RUNX1 complex induces the transcription of HDAC2 to induce chemoresistance and stemness in breast cancer cells." (PMID 35494005, 2022). "HDAC2 protein overexpression was detected in human gastric, prostate, and breast cancers." (PMID 35359455, 2022). "Interestingly, HDAC2 has been reported to promote the development of tamoxifen resistance in breast cancer cells by downregulating miR‐125a‐5p." (PMID 35060363, 2022). "However, the levels of EZH2 and HDAC2 increased with the increase in the malignancy of breast cancer." (PMID 35892859, 2022).
breast cancer (continued). "The invalidation of HDAC2 and HDAC7 has been reported to be associated with proliferation arrest respectively in MCF-7 breast cancer cell line and in mucoepidermoid carcinoma cells, but not yet investigated on the potential induction of the senescent phenotype in normal cells." (PMID 34253688, 2021). "We also found that many proteins in the network took part in tumor development; for example, PHIP drives glioblastoma motility and invasion, HDAC2 regulates breast cancer progression and proliferation, and ZFN292 participates in hepatoma proliferation and vasculogenic mimicry." (PMID 34649520, 2021). "Our results indicate that HDAC2 also has a role in immune evasion of breast cancer cells." (PMID 34365463, 2021). "Additionally, previous studies reported that higher HDAC2 expression was correlated with metastasis, aggressiveness, and poor prognosis in breast cancer." (PMID 34365463, 2021). "HDAC2 is an important histone deacetylase that is overexpressed in breast cancer." (PMID 34993131, 2021). "HDAC2 enables the motility of breast cancer cells by upregulating Matrix Metalloproteinase 2 (MMP2) and N-cadherin and HDAC3 associates with Epidermal Growth Factor Receptor (EGFR) and c-Src to promote breast cancer cell invasion." (PMID 33803458, 2021). "Furthermore, HDAC2 knockout reduced IFNγ-induced PD-L1 expression, lymphocyte infiltration, and retarded tumor growth and metastasis in the breast cancer mouse models." (PMID 34365463, 2021). "In addition to BC, the abnormal overexpression of HDAC2 has been detected in a number of types of cancer, including gastric cancer, ovarian cancer and breast cancer." (PMID 32774482, 2020). "Indeed, it has been shown that HDAC2 overexpression correlates with a poor prognosis of breast cancer patients." (PMID 30868056, 2019). "Histonedeacetylases (HDACs) control the gene expression and cellularsignalling and histone deacetylases 2 (HDAC2) is over expressed insolid tumors including colon cancer, lung cancer, cervicalcarcinoma, breast cancer, and kidney/cervix cancer and also inAlzheimer's disease 5-7." (PMID 31312074, 2019). "Also, HDAC2 knockdown in breast cancer cells leads to inhibition of proliferation and USP4 knockout results in the retarded growth of mouse embryonic fibroblasts (MEF)." (PMID 30071870, 2018). "For examples, Twist1 recruits Mi2/NuRD complex including HDAC1 and HDAC2 to the E-cadherin and ERα promoters causing histone deacetylation and chromatin condensation, further reducing transcript levels, thus to promote EMT and metastasis of breast cancers." (PMID 28394356, 2017). "In our model of less aggressive breast cancer, the significant reduction of HDAC2 expression was in accordance to colon cancer where HDAC2 was reported to share similar feature to those of tumor-suppressor genes when mutation-loss of HDAC2 function lead to oncogenesis." (PMID 28785170, 2017). "Thus, our results support the role of HDAC2 as another epigenetic regulator for Nav1.5 and nNav1.5 expression in breast cancer." (PMID 28785170, 2017). "In addition, HDAC2 down-regulation also increased the expression of miR-125a-5p in the tested breast cancer cells." (PMID 29326587, 2017). "Linkage between HDAC2 modulation and H4k16 acetylation has been shown in breast cancer." (PMID 26683361, 2016). "Accordingly, when HDAC2 silencing was induced in MDA-MB231 breast cancer cells using a different sh2 target sequence and a different expression vector, we obtained similar levels of H3 and H3K56 acetylation and a similar decrease in acetylation levels of H4K16." (PMID 25473896, 2015). "As compensatory responses in protein expression are reported between the HDAC1 and HDAC2 isoenzymes in conditional knockout mice, and on siRNA depletion in osteosarcoma and breast cancer cell lines, we tested if this was also the case in A549 lung cancer cells." (PMID 25970771, 2015).
breast cancer (continued). "Histone deacetylases (HDACs) control the gene expression and cellular signaling and histone deacetylases 2 (HDAC2) is overexpressed in solid tumors including colon cancer, lung cancer, cervical carcinoma, breast cancer, and kidney/cervix cancer and also in Alzheimer's disease." (PMID 25525429, 2014). "Furthermore, our colony formation assay results indicated that HDAC2 may serve as a potential therapeutic target for breast cancer." (PMID 37483962, 2023). "In summary, these results indicate that histone modification participates in the regulation of PDK1 by inhibiting miR-148a, and the existence of the HDAC2/EZH2/miR-148a/PDK1 regulatory axis may be important in breast cancer development and therapeutic resistance." (PMID 35892859, 2022). "Notably, HDAC1 and HDAC2 were predominantly located in the nucleus of breast cancer cells." (PMID 32686908, 2020). "However, the molecular role/s of HDAC2 in regulating ER+ breast cancer cell survival and hormone therapy resistance induction is still largely unknown." (PMID 29326587, 2017). "Importantly, ectopic over-expression of survivin attenuated the cell viability reduction effect caused by HDAC2 siRNA in MCF7, MCF7-TamC3, and ZR-75-1 cells, confirming the pro-survival role of the HDAC2-mTOR-survivin signaling pathway in ER+ breast cancer cells." (PMID 29326587, 2017). "HDAC1 and HDAC2 (ranked at 3 and 4), among class I HDACs, were reported to regulate the changes in histone acetylation and were associated with HDAC inhibitors that were expected to reverse hypoacetylation levels observed even at the early stages of breast cancer progression." (PMID 21799737, 2011). "Chidamide, a selective inhibitor targeting HDAC1, HDAC2, HDAC3, and HDAC10, has been approved for treating relapsed/refractory peripheral T cell lymphoma and hormone receptor-positive, HER2-negative breast cancer after endocrine therapy." (PMID 41049003, 2025). "HDAC1, HDAC2, and HDAC8 were found to form a complex with EMT-TF Snail and induce EMT in breast cancer cells to promote migration." (PMID 40165290, 2025). "In breast cancer cells, FOXO3a displaces FOXM1 and recruits histone deacetylase 2 (HDAC2) to the VEGF promoter, leading to reduced histone acetylation and suppressed VEGF transcription." (PMID 39519130, 2024). "The HDAC proteins were validated by many HDAC inhibitors in the colony formation assay, and the genes HDAC2 and HDAC3 have been found to be differentially expressed in human breast cancer and strongly expressed in aggressive tumor subgroups." (PMID 38935814, 2024). "For instance, in the context of breast cancer, ARAP1-AS1 was observed to enhance the expression of HDAC2 by binding to miR-2110." (PMID 39090630, 2024). "This study emphasized specific role of epigenetic modifiers like DNMT1 and HDAC1 & HDAC2 on proliferation and apoptosis, as well as aggressiveness, invasion and metastasis in terms of EMT through centrosome amplification in breast cancer." (PMID 36774386, 2023). "Although, either silencing of DNMT1 or inhibition of HDAC1 & HDAC2 were able to reduce cell migration even after 24 h, both knockdown of DNMT1 and TSA treatment synergistically inhibited migration of MDA-MB-231 breast cancer cells significantly higher." (PMID 36774386, 2023). "Correlation of the function of certain genes with underlying cellular metabolites was interpreted by observing cell survival and migration pattern of MDA-MB-231 breast cancer cells after knockdown of DNMT1 and specific inhibition of HDAC1 & HDAC2." (PMID 36774386, 2023). "We observed variations in the expression levels of HDAC1, HDAC2, HDAC3 and HDAC10 mRNAs targeted by chidamide among the ER+ breast cancer cell lines." (PMID 37445654, 2023). "Further mechanistic insights revealed the down-regulation of HDAC2 and HDAC3 and enhanced levels of H3K4Me3 (trimethylated lysine 4 of histone 3) in the promoter region of p21 in both breast cancer cell lines." (PMID 36765652, 2023).
breast cancer (continued). "Immunohistochemical expression of H3K9Ac, H4K12Ac, HDAC1, HDAC2 and HDAC6 in 61 samples of simple mammary carcinoma in female dogs." (PMID 38028583, 2023). "All samples of simple breast carcinoma expressed the proteins H3K9Ac, H4K9Ac, HDAC1, and HDAC2 with mean scores of 4.96, 9.86, 5.98, 7.67, respectively, in the immunohistochemical reactions." (PMID 38028583, 2023). "The present study aims to correlate the expression of H3K9Ac, H4K12Ac, HDAC1, HDAC2 and HDAC6 in simple mammary carcinomas in dogs with clinicopathological parameters and overall survival time." (PMID 38028583, 2023). "To further test the regulation of miR-148a with HDAC2 and EZH2, we analyzed the expression levels of HDAC2, EZH2, and miR-148a in twenty pairs of human breast cancer tissues and their corresponding normal breast tissues." (PMID 35892859, 2022). "Overexpression of HDAC2 was highly correlated with high tumor grade, positive lymph node status, and dismal prognosis, and the HDAC inhibitor showed antitumor effects on breast cancer lines by mediation of miR‐182." (PMID 35060363, 2022). "HDAC-2 has been found to be up-regulated in HCC, lung, pancreatic, colorectal and breast cancer and it has also been correlated to chemotherapy resistance." (PMID 35629174, 2022). "Significantly higher expression levels of HDAC2 and EZH2 were detected in breast cancer tissues than those in normal tissues, which was consistent with the IHC results for breast cancer and normal breast tissues from the Human Protein Atlas Database." (PMID 35892859, 2022). "They revealed the high expression levels of these class I HDACs, and IHC results for HDAC1, HDAC2, HDAC3, and HDAC8 were positive in 17 (85%), 20 (100%), 20 (100%), and 17 (85%) of 20 breast cancer cases, respectively." (PMID 36188615, 2022). "HDAC2 can be recruited by PELP1 to miR-200a and miR-141 promoters and suppress their expression to promote EMT in breast cancer." (PMID 34993131, 2021). "As a transcriptional inhibitor of VEGF gene, Kruppel-like Factor 4 (KLF4) recruits HDAC2 and HDAC3 to the VEGF gene promoter for suppressing VEGF gene transcription in breast cancer." (PMID 34307380, 2021). "In the current study, we identified that PD-L1 and HDAC2 were overexpressed in TNBC, and there was a significant correlation between those two genes from the breast cancer online dataset." (PMID 34365463, 2021). "More recently, the overexpression of HDAC2 was found to be correlated with tumor EMT process, metastasis, higher Ki-67 level, and multidrug-resistance protein expression in breast cancer." (PMID 34365463, 2021). "The recent study revealed that upregulation of EphA2 by HDAC2 and HDAC4 plays a crucial role in breast cancer, and HDACs-EphA2 signaling axis is a promising therapeutic target for advanced breast cancer." (PMID 32376822, 2020). "The recent study revealed that HDAC2 and HDAC4 promote the oncogenicity of breast cancer cells by upregulating EphA2 expression and phosphorylation." (PMID 32376822, 2020). "HDAC1, HDAC2, and cytoplasmic HDAC3 all displayed typical oncogenic characteristics and were independent prognostic factors for the overall survival of breast cancer patients." (PMID 32686908, 2020). "In multivariate Cox regression analysis, HDAC1, HDAC2, or cytoplasmic HDAC3 was still an independent prognostic factor for the overall survival of breast cancer patients after correction for tumor size, histological grade, lymph node status, ER and PR." (PMID 32686908, 2020). "Previous studies have shown that patient breast cancer samples that co-express high levels of LSD1 and histone deacetylases (SIRT1, HDAC2) have decreased survival." (PMID 31534138, 2019). "We previously reported the involvement of HDACs (HDAC2 and HDAC3) in KCa3.1 transcription in human breast cancer cells." (PMID 30262728, 2018). "We previously reported epigenetic modifications to KCa3.1 by HDAC2 and HDAC3 in human breast cancer cells." (PMID 30262728, 2018).
breast cancer (continued). "HDAC1, HDAC2, HDAC3, and HDAC6 are highly expressed in breast cancer cells, and the inhibition of HDAC2 down-regulates the KCa1.1 gene." (PMID 29713287, 2018). "Both overexpression and knockdown of TRPS1 assays were performed to examine the effect of TRPS1 on histone deacetylase 2 (HDAC2) protein level and luminal breast cancer cell proliferation." (PMID 30071870, 2018). "In doing so, the expression level of Nav1.5, nNav1.5, REST, HDAC1, HDAC2, and HDAC3 were measured and compared between the less aggressive human breast cancer cells, MCF-7 and the aggressive, MDA-MB-231 cells." (PMID 28785170, 2017). "The effect of HDAC inhibitor, trichostatin A (TSA), on Nav1.5, nNav1.5, HDAC1, HDAC2, HDAC3, REST, MMP2 and N-cadherin gene expression and on cell motility and migration of the less metastatic human breast cancer cells, MCF-7, were investigated." (PMID 28785170, 2017). "This study focused on examining the role of REST, HDAC1, HDAC2, and HDAC3 on influencing the expression of Nav1.5 and nNav1.5 in breast cancer that promote aggressiveness." (PMID 28785170, 2017). "The expression patterns of HDAC1, HDAC2, and HDAC3 have been evaluated in different types of cancers, including gastric cancer, liver cancer, prostate cancer, breast cancer, renal cell cancer, ovarian and endometrial carcinomas." (PMID 28785170, 2017). "Further molecular analysis revealed that HDAC2 and HDAC5 positively modulates the expression of survivin, and negatively regulates the expression miR-125a-5p, in ER+ MCF7, MCF7-TamC3, and ZR-75-1 breast cancer cells." (PMID 29326587, 2017). "HDAC2 siRNA and HDAC5 siRNA also promoted the death of MCF7, MCF7-TamC3, and the ER+ tamoxifen-sensitive ZR-75-1 breast cancer cells." (PMID 29326587, 2017). "Importantly, retrospective Kaplan–Meier analysis and ROC analysis showed that high HDAC2 and survivin, and low miR-125a-5p, expression levels significantly correlate with poor overall or relapse-free survival in tamoxifen or endocrine therapy-treated ER+ breast cancer patients." (PMID 29326587, 2017). "In summary, we showed that the combined expression level of LSD1, HDAC2 and SIRT1 is a good predictor for OS and RFS in breast cancer patients." (PMID 25139823, 2014). "Immunohistochemical staining for LSD1, HDAC2 and SIRT1 was performed on tissue microarrays of tumor and corresponding normal formalin-fixed paraffin-embedded tissues from breast cancer patients." (PMID 25139823, 2014). "Our study identified combined expression levels of the histone-modifying enzymes LSD1, HDAC2 and SIRT1 as an independent prognostic factor for patient survival and tumor relapse in breast cancer patients." (PMID 25139823, 2014). "We investigated tumor expression levels of histone-modifying enzymes LSD1, HDAC2 and SIRT1 in relation with patient survival and tumor relapse in a retrospective cohort of 460 breast cancer patients." (PMID 25139823, 2014). "In breast cancer, high (IRS 9–12) nuclear expression of HDAC1, HDAC2 and HDAC3 was observed in 32.7%, 24.1% and 31.7% of cases, respectively." (PMID 23627572, 2013). "Our study demonstrates a differential expression of HDAC1, HDAC2 and HDAC3 using immunohistochemistry in breast cancer." (PMID 23627572, 2013). "In a pilot study, we found that the MCF7 cell line-derived, ER+, estrogen-independent, and tamoxifen-resistant, MCF7-TamC3 breast cancer cells exhibit increased expression of two epigenetic regulators, HDAC5 and HDAC2, compared to the parental ER+ MCF7 breast cancer cells." (PMID 39991577, 2025). "Nevertheless, patient-derived triple negative breast cancer tumor samples are not included in the majority of these studies; instead, HDAC-2 expression has been examined in breast cancer cell lines or xenograft tumor models." (PMID 38201636, 2024). "In human breast cancer, HDAC1, HDAC2, and HDAC3 have been found to be differentially expressed." (PMID 38935814, 2024).